IL6 (interleukin 6)
Diseases named in the same sentence as IL6 in open-access papers (continued):
Sharing a sentence is not in itself a finding about the gene and the disease.
delirium (continued). "Interleukin-6 was increased in patients with delirium [54.6 (31.0,87.8) pg/ml vs. 14.7 (7.4,50.6) pg/ml, p = 0.03 at day 3 and 63.6 (20.2, 214.5) pg/ml vs. 11.0 (5.3, 27.6) pg/ml, p < 0.001 at day 7]." (PMID 39352661, 2025). "Peripheral inflammation is a well-established trigger of delirium, and IL-1, IL-1β, IL-6, IL-8, tumor necrosis factor (TNF), and prostaglandin E2 (PGE2) stimuli trigger tissue macrophage and blood monocyte activation and secretion of inflammatory mediators." (PMID 41459337, 2025). "Previous systematic reviews and meta-analyses have predominantly focused on a limited set of inflammatory and neuronal injury-related biomarkers, such as IL-6, CRP, cortisol, and S100β, in relation to delirium risk." (PMID 40889075, 2025). "Pre-operative IL-6 also had 61.3% sensitivity and 79.4% specificity of patients developing post-operative delirium." (PMID 39910669, 2025). "Dexmedetomidine demonstrated a dose-dependent effect on TNF-α modulation, delirium incidence, and opioid consumption; however, its influence on IL-6 levels and extubation time was less pronounced." (PMID 40283079, 2025). "A meta-analysis study confirmed that IL-6 was a consistent predictor for delirium in the surgical setting." (PMID 39860413, 2025). "Compared to the experimental group, the control group had a higher IL-6 concentration and a higher incidence of delirium." (PMID 38302882, 2024). "For example, IL-6 presents odds ratio in the delirium population that range between 0.84 and 5.2, while the C-reactive protein shows an odds ratio spanning from 0.45 to 5.73, indicating the limited specificity of these biomarkers." (PMID 38921436, 2024). "Chronic low-grade inflammation, marked by elevated interleukin-6 (IL-6) and tumor necrosis factor-alpha (TNF-α), disrupts neurotransmitter balance and impairs brain function, increasing delirium risk." (PMID 39737160, 2024). "Among the unique proteins, we focused on the top 13 most investigated proteins (IL-6, CRP, IL-8, S100B, IL-10, TNF-a, IL-1b, Cortisol, MCP-1, GFAP, IGF-1, IL-1ra, and NFL) that are significantly associated with delirium." (PMID 39700095, 2024). "Plasma IL-6 levels are correlated with delirium intensity and length in critically ill individuals, indicating that systemic inflammation plays a role in the onset and progression of delirium." (PMID 39700095, 2024). "Particularly, regarding its potential to serve as a delirium marker, IL-6 is one of the cytokines that has been examined the most among the included studies." (PMID 39700095, 2024). "The findings from this clinical study are consistent with these prior preclinical findings implicating IL-6-trans-signaling as a principal pathway in delirium pathogenesis." (PMID 38778074, 2024). "Though incongruent with prior clinical trials, the lack of improvements in survival or ventilator duration among tocilizumab-treated patients in our study supports an independent beneficial effect of peripheral IL-6 antagonism on delirium/coma outcomes." (PMID 38778074, 2024). "A study on patients with delirium found that interleukin-6 (IL-6) levels were significantly lower in patients treated with melatonin than in those receiving a placebo." (PMID 39558437, 2024). "Several studies have demonstrated a link between proinflammatory cytokines (C-reactive protein, interleukin-6, and tumor necrosis factor-alpha) and delirium." (PMID 39604840, 2024). "This is supported by greater serum concentrations of CRP and IL-6 in patients who developed delirium during hospitalization." (PMID 37360340, 2023). "Some proteins and pathways, including plasma IL-6 and IL-8, are common to delirium in both age groups but older delirious patients had changes in more proteins and pathways than middle-aged subjects with the same clinical phenotype." (PMID 37156856, 2023). "Further, in pre-clinical models of delirium, targeting cytokines, such as IL-6, have shown therapeutic promise." (PMID 36803215, 2023).
delirium (continued). "This study evaluated the effect of nine genetically predicted inflammatory factors (TNF-α, CPR, IL-1α, IL-1β, IL-2, IL-6, sIL-6Rα, Soluble gp130, and IL-8) on delirium." (PMID 37649721, 2023). "Although current evidence does not favour the use of any particular biomarker, serum CRP, TNF-α, and IL-6 were the most consistent biomarkers of delirium in older patients." (PMID 37251808, 2023). "Inflammatory mediators such as IL-1B, IL-6, IL-8, IL-10, TNF-alpha, and C-reactive protein (CRP), have all shown associations with delirium." (PMID 36803215, 2023). "Nevertheless, the findings of studies are conflicting, with some reporting higher plasma IL-6 levels in individuals with delirium and others detecting different results." (PMID 37373482, 2023). "Our systematic review identified 17 studies that showed elevated IL-6 serum concentrations as a predictor of delirium." (PMID 37360340, 2023). "The additional measurement of interleukin (IL)-6, IL-8, IL-10 and tumor necrosis factor-α increases the accuracy to predict delirium and an unfavorable outcome." (PMID 37744876, 2023). "The IL-6 signaling pathway has been extensively investigated in the pathogenesis and progression of delirium." (PMID 37649721, 2023). "It has also been shown that decreasing the expression of IL-6 and upregulating the expression of IL-10 in the peripheral blood, hippocampus, and prefrontal cortex reduces microglia activation and reduces delirium-like behavior in mice." (PMID 37025488, 2023). "The addition of Delirium and IL6 to the scoring systems improved their discriminative ability, resulting in AUC values of 0.92 for MRS, 0.87 for CALL, and 0.84 for PREDI-CO." (PMID 37329431, 2023). "Overall, pooled analysis showed a significant increase in some serum biomarkers (i.e., CRP, TNF-α, and IL-6) of patients who developed delirium (OR = 1.88, 95% CI 1.01 to 1.637; I2 = 76.75%)." (PMID 37251808, 2023). "There is an increased systemic production of interleukin-1 α (IL-1α), IL-1β, IL-6, IL-10, and tumor necrosis factor α (TNF-α), which are implicated in the pathogenesis of delirium." (PMID 36030220, 2022). "Among various cytokines, IL-6 has been frequently studied as a potential predictor of delirium in urinary tract infection, sepsis, acute lung injury, and perioperative animal models." (PMID 36030220, 2022). "Although various cytokines and inflammatory mediators are upregulated in AKI, recent animal studies suggest that the use of systemic IL-6 inhibition mitigates delirium-like phenotypes in urinary tract infection, acute lung injury, and postoperative states." (PMID 36030220, 2022). "The causal role of IL6 and IL6-induced IL12 and IL13 in mediating the effect of serum from delirium patients on the neurogenic outcomes is confirmed by the use of an antibody against these cytokines in our experiments." (PMID 36195636, 2022). "In this respect, previous reports showed that increases in peripheral levels of C-reactive protein (CRP), interleukin-6 (IL-6), CXCL8 (IL-8), and tumor necrotic factor (TNF)-α are associated with the onset of post-operative delirium." (PMID 35641947, 2022). "IL-6 seems to be of particular interest as it seems to be a consistent predictor of delirium in surgical samples." (PMID 35802656, 2022). "Compared to controls, mice treated with 17β-estradiol had less neuronal injury, improved delirium-like behaviors, and less plasma and frontal cortex IL-6." (PMID 36380004, 2022). "We previously demonstrated a pathological role for interleukin-6 (IL-6) in mediating delirium-like phenotypes in a murine model of UTI." (PMID 36380004, 2022). "We previously published findings demonstrating a pathological role for interleukin-6 (IL-6) in mediating delirium-like phenotypes in response to UTI13." (PMID 36380004, 2022). "It is probable that IL-6 plays a key role in the development of the inflammatory cascade in the genesis of delirium." (PMID 35140282, 2022).
delirium (continued). "Tissue samples from patients with delirium showed activated microglia and astrocytes and elevated levels of IL-6 in the hippocampus." (PMID 35711904, 2022). "To further understand the role that inflammation plays in delirium, we measured levels of inflammatory markers, and found that increased IL-6 and TNF-α were significantly associated with delirium development." (PMID 36118695, 2022). "The pro-inflammatory cytokines, IL-6, TNF-α, IL-1α, IL-1β, have been implicated in delirium-like behavioral changes, such as impaired concentration, diminished motivation, and psychomotor retardation in critically ill patients." (PMID 36030220, 2022). "Other study described median preoperative IL-6 levels in the patients with postoperative delirium vs. the non-delirium group as 9 pgmL-1 vs. 3.4 pgmL-1." (PMID 33918634, 2021). "Nevertheless, the findings of these studies are conflicting, with some studies reporting higher plasma IL-6 levels in individuals with delirium and others detecting different results." (PMID 34044881, 2021). "In summary, this study provides first evidence that systemic IL-6 mediates delirium-like phenotypes in an animal model of UTI." (PMID 34711238, 2021). "A recent systematic review has shown that IL-1β, IL-6, IL-8, IL-10, and IFN-γ are significantly associated with delirium onset, displaying higher levels, both in plasma and CSF, in relation to baseline." (PMID 34736422, 2021). "Recent studies have demonstrated associations between traditional inflammatory markers and delirium, such as C-reactive protein (CRP), interleukin (IL)-6, IL-8, IL-2, and tumor necrosis factor (TNF)." (PMID 34034650, 2021). "This study provides evidence demonstrating a pathological role for the IL-6 signaling pathway in mediating functional and structural delirium-like phenotypes in an animal model of UTI." (PMID 34711238, 2021). "To examine a role for the delirium-relevant inflammatory marker, IL-6, we first characterized the time course of IL-6 release in the systemic circulation over 72 h of UTI." (PMID 34711238, 2021). "The anesthesia/surgery induced greater postoperative delirium-like behavior, increased brain IL-6 levels, decreased PSD-95 and synaptophysin levels, and mitochondrial dysfunction in 18 than 9 months old mice." (PMID 31974315, 2020). "We found that the anesthesia/surgery was able to induce age-dependent postoperative delirium-like behavior, changes in gut microbiota, levels of brain IL-6 and synaptic marker, and mitochondrial dysfunction in the mice." (PMID 31974315, 2020). "The two most common biomarkers in these six studies that reported a positive association with delirium were CRP (n=3) and IL-6 (n=3)." (PMID 32321448, 2020). "In critical care patients, plasma IL-6 is related to the severity and duration of delirium, suggesting that systemic inflammation is involved in the occurrence and development of delirium." (PMID 33192455, 2020). "In fact, aging and chronic stress elevates IL-6 amongst other mediators and these cytokines can further prime microglia cells and possibly impair neuro-immune circuits of relevance to delirium-like behavior." (PMID 31911786, 2019). "The most replicated finding, albeit not confirmed by some researchers, is the elevated blood interleukin (IL)-6 level during delirium." (PMID 29669581, 2018). "After correction for monocyte count, patients with delirium had reduced LPS-induced TNFα, IP-10, IL-1β, IL-6, and IL-12 release." (PMID 29669581, 2018). "We focused on POD2 because this was the time period that we found significant IL-6 effect on postoperative delirium (the matched analysis with conditional logistic regression)." (PMID 28587598, 2017). "The main exposure was IL-6 concentration (pg/ml) from blood sampled at three time points before delirium occurred." (PMID 28587598, 2017).
delirium (continued). "Preoperatively, plasma IL-6 was 14-fold higher at baseline in the one patient who developed delirium; for calprotectin, more than 5-fold higher values, and for plasma, MIP-1β more than 3-fold higher values were observed." (PMID 27577265, 2016). "That study also found that the serum levels of the pro-inflammatory cytokines IL-6 and IL-8 were higher in patients with delirium." (PMID 25943983, 2015). "The simultaneous comparison of cortisol, IL-6, IL-8, and S100B protein revealed that the highest levels of cortisol and IL-8 were observed before delirium but the highest levels of IL-6 and S100B were observed during delirium." (PMID 26417595, 2015). "In this study, there was a correlation between elevated levels of IL-6 and delirium, both of which were present at reduced levels in the FTS treatment group." (PMID 24337734, 2014). "We found that enhanced IL-6 level correlated with the development of postoperative delirium and peaked on POD 1 in the elderly patients undergoing colorectal surgery." (PMID 24337734, 2014). "The lower incidence of delirium is at least partly attributable to the reduced systemic inflammatory response mediated by IL-6." (PMID 24337734, 2014). "As proinflammatory cytokines particularly IL-6 have been reported to be involved in the development of postoperative delirium, we determined the serum IL-6 levels in both the FTS and the traditional groups." (PMID 24337734, 2014). "Excessive release of proinflammatory cytokines such as TNF-α, IL-1, IL-6, and IL-8 during systemic inflammation can affect brain functions and promote the development of delirium." (PMID 24337734, 2014). "Together, these results showed that enhanced IL-6 level correlated with the development of postoperative delirium in the elderly patients undergoing colorectal surgery." (PMID 24337734, 2014). "It has been reported that the serum levels of an inflammatory biomarkers, including interleukin-6 (IL-6), were positively correlated to the incidence of delirium." (PMID 24337734, 2014). "Increased serum levels of the pro-inflammatory cytokines interleukin-6 and -8 (IL-6, IL-8) were found in elderly hip fracture patients with delirium." (PMID 25124807, 2014). "In patients with delirium, like Alzheimer’s patients, blood and brain IL-6 are higher compared to controls." (PMID 24093540, 2013). "Concentrations of Flt-3L (P=0.021), IL-1ra (P=0.032), and IL-6 (P=0.005) were significantly lower in patients who developed delirium postoperatively." (PMID 24093540, 2013). "Despite the limited power of this exploratory study, we found significantly lower levels of Flt-3L, IL-1ra, and IL-6 and distinct trends for lower levels of IL-15 and higher levels of IP-10 in CSF of patients with postoperative delirium." (PMID 24093540, 2013). "Concentrations of Fms-like tyrosine kinase-3 (P=0.021), Interleukin-1 receptor antagonist (P=0.032) and Interleukin-6 (P=0.005) were significantly lower in patients who developed delirium postoperatively." (PMID 24093540, 2013). "Immunotherapy with cytokines can induce delirium (IL-2, IFN) and increased systemic cytokines and acute phase proteins (IL-6, IL-8, CRP) are associated with delirium post hip fracture." (PMID 20471138, 2012). "Studies have shown that changes in the inflammatory response and neurological injury‐related biomarkers were associated with the occurrence and duration of the emergence of delirium in elderly patients, and IL‐6 had a significant correlation with the duration of emergence delirium." (PMID 41552378, 2026). "Elevated preoperative blood NfL and Glial Fibrillary Acidic Protein (GFAP) levels were independently associated with increased risk of postoperative delirium, with NfL and GFAP predicting postoperative delirium even after adjustment for age, sex, dementia, frailty, and IL-6." (PMID 41440533, 2025).
delirium (continued). "Preoperative elevation of IL-6 (OR 2.32, 95% CI 1.54–3.49), CXCL8 (OR 3.05, 95% CI 1.86–4.99), and C-reactive protein (OR 2.13, 95% CI 1.60–2.83) independently predict delirium risk across surgical populations, suggesting baseline inflammatory status as a modifiable risk factor." (PMID 41375722, 2025). "In patients with delirium, it was demonstrated that pro-inflammatory cytokines, such as IL-6, IL-1α, IL-1β, and TNF-α, are associated with delirium-like behavioral disturbances, such as diminished concentration, altered motivation, and decreased psychomotor activities." (PMID 41156174, 2025). "This suggests that the pathophysiology of delirium during liver resection may involve more complex inflammatory mechanisms beyond IL-6 that warrant further investigation." (PMID 41332466, 2025). "Additionally, patients with delirium had higher plasma IL-6 concentrations, and there was a positive correlation between S100B and IL-6 levels." (PMID 39201697, 2024). "We recently demonstrated in pre-clinical mouse models of acute lung injury and mechanical ventilation a novel pathological link between elevated peripheral IL-6 levels and delirium-like phenotypes, encompassing both structural and functional brain modifications." (PMID 38778074, 2024). "In this study, we combined esketamine with sufentanil to observe the postoperative analgesic effect and serum IL-6 concentration, as well as the reduction of pain and inflammation levels, thus reducing the incidence of postoperative delirium in elderly patients." (PMID 38302882, 2024). "IL-6, IL-8, IL-10, IL-18, TNF-α, and chemokines (CCL2, CCL3, CXCL1, and CXCL10) have also been reported to be elevated in ICU delirium patients and are associated with delirium severity." (PMID 39308447, 2024). "Moreover, there is evidence that increased levels of IL-6 are related to a diminished cognitive recovery after delirium." (PMID 37373482, 2023). "Unknown is whether cognitive deterioration could be mediated by IL-6-induced delirium and whether IL-6 inhibition could promote recovery after POD." (PMID 37373482, 2023). "Although the evidence on IL-6 and its association with POD is partially contested, our data suggest that higher IL-6 levels postoperatively, after adjusting for baseline concentration, are related to an increased risk of developing delirium." (PMID 37373482, 2023). "By incorporating IL-6 and delirium into the scores, the highest level of performance was achieved." (PMID 37329431, 2023). "The results of this MR analysis did not support that peripheral TNF-α, CRP, IL-1α, IL-1β, IL-2, IL-6, sIL-6Rα, soluble gp130, and IL-8 were causally associated with delirium." (PMID 37649721, 2023). "Notably, in our study, the postoperative plasma IL-6 levels peaked on the second postoperative day, which was consistent with an earlier report that showed increased incidence of delirium on the second postoperative day." (PMID 36750929, 2023). "Four studies could be included in the meta-analysis of IL-6; the results showed a significant increase in this biomarker in serum (OR = 1.88, 95% CI 1.01 to 1.637) in patients who developed delirium, with high heterogeneity (τ2 = 0.31, I2 = 76.75%)." (PMID 37251808, 2023). "Only 6 studies were eligible for the meta-analysis, pooled results showed a significant increase in some serum biomarkers (C-reactive protein [CRP], tumour necrosis factor alpha [TNF-α] and interleukin-6 [IL-6]) among patients with delirium (odds ratio = 1.88, 95% CI 1.01 to 1.637; I2 = 76.75%)." (PMID 37251808, 2023). "Currently, one of the most well-studied cytokines in delirium is IL-6." (PMID 36803215, 2023). "The findings of this study suggest that the IL-6 trans-signaling pathway may be enhanced in the supine position and consequently mediate delirium-relevant neuronal injury induced by VILI in the supine but not the prone position." (PMID 36405620, 2022).